PON1 (paraoxonase 1)
Diseases named in the same sentence as PON1 in open-access papers (continued):
Sharing a sentence is not in itself a finding about the gene and the disease.
prostate carcinoma (18 papers, 2005 to 2025). A carcinoma that arises from epithelial cells of the prostate gland. "In a meta-analysis published in 2019, it was reported that there are significant associations between PON1-L55M genetic variation and other cancers such as hematologic cancer and prostate cancer." (PMID 31983193, 2020). "As for PON1-Q192R, it has been revealed to suppress expression in lung and pancreatic cancer and reduce the risk of breast and prostate cancers." (PMID 31467900, 2019). "Merging of NPs and VGs yields NP (The PON1 102V allele), VG (appears to be associated), NP (an increased risk for prostate cancer)." (PMID 27073839, 2016). "In Example-2, the base NPs and base VGs are NP (The PON1 102V allele), VG (appears), VG (to be associated), NP (an increased risk), NP (prostate cancer)." (PMID 27073839, 2016). "Recently, a meta-analysis suggested that the PON1 R192Q polymorphism is a significant risk factor for all cancers, including breast, brain and prostate cancers, especially in Asian populations." (PMID 25741997, 2015). "More recently, the presence of the variant alleles of the Q192R and L55M SNPs of PON1, both of which result in an amino acid replacement that alters PON1 activity, were found associated with a 18–29% increased risk of aggressive prostate cancer." (PMID 22666600, 2012). "Concerning PON1 L55M, it is also associated with a higher risk of prostate cancer." (PMID 35453382, 2022). "Similarly, the PON1 192Q allele has been reported to reduce the risk of bladder cancer, ovarian cancer, and B-cell lymphoma; in contrast, it has been reported to increase the risk of lung, breast and prostate cancers." (PMID 25741997, 2015). "Genes linked to prostate cancer susceptibility, including RNASEL, MSR1 and MIC1, found in areas associated with familial prostate cancer, as well as TLR4, MIC1, PON1, BRCA2, CHEK2 and OGG, have been identified as contributors to prostate cancer development." (PMID 38971935, 2025). "Research has shown that androgens can significantly increase the expression of CYP4F2 and CYP4F3 through androgen receptor (AR) in prostate cancer cells, while PON1 activity is modulated by estrogen through HDL metabolism pathways." (PMID 40115349, 2025). "We investigated changes in the activity of antioxidant paraoxonase-1 (PON1) in patients with prostate cancer (PCa) undergoing radiotherapy (RT), as well as the relationship of the PON1 activity with the degree of PCa advancement." (PMID 36829771, 2023). "We investigated changes in the activity of PON1 in patients with prostate cancer (PCa) undergoing RT, and the relation of PON1 activity to the risk of recurrence after RT." (PMID 35204228, 2022). "In agreement with our results, a recent study reported that patients with prostate cancer recurrence had significantly higher post-RT serum PON1 activity than those who were recurrence-free." (PMID 36552602, 2022). "The aim of this study was to investigate the relation between serum PON1 activity and the relapse of prostate cancer in patients undergoing RT." (PMID 35204228, 2022). "Example-2 matches the first of these rules, where NP1 matches the base NP “the PON1 102V allele” which will allow us to identify the mutation and NP2 matches the merged phrase “an increased risk for prostate cancer” which is used to identify the disease." (PMID 27073839, 2016). "NP1 is matched with the phrase “The PON1 102V allele” and NP2 is matched with “an increased risk for prostate cancer”, which is a merged NP." (PMID 27073839, 2016). "In recent years, the serum PON1 activity has been reported to be reduced in several types of malignancies, such as lung cancer, gastrointestinal cancer, breast and prostate cancer, bladder cancer, central nervous system tumors, non-Hodgkin’s lymphoma, and acute lymphoblastic lymphoma." (PMID 36829771, 2023). "Prevalence of GSTP1, PON1/192, PON1/55 and CYP17 polymorphisms and risk of prostate cancer (Pca)." (PMID 24040147, 2013).
prostate carcinoma (continued). "Conversely, serum PON1 activity has been found to be increased in a group of 23 Turkish patients with prostate cancer, while no changes in lipid peroxidation markers were observed." (PMID 29176871, 2017).
endothelial dysfunction (17 papers, 2013 to 2025). In vascular diseases, endothelial dysfunction is a systemic pathological state of the endothelium (the inner lining of blood vessels) and can be broadly defined as an imbalance between vasodilating and vasoconstricting substances produced by (or acting on) the endothelium. "The findings regarding PON1, homocysteine, and microalbuminuria fit well within existing evidence linking oxidative stress, endothelial dysfunction, and early renal damage to cardiovascular risk." (PMID 41597318, 2025). "The association of HDL-C PON1 and endothelial dysfunction depends largely on the molecules with exact damaging effect on NO synthase coupling." (PMID 24222847, 2013). "“Dysfunctional HDL,” on the contrary, has reduced Paraoxonase 1 enzyme activity and not only fails in its mission but also potentially leads to greater formation of oxidized lipids/lipoproteins to cause endothelial dysfunction." (PMID 24222847, 2013). "When considered alongside homocysteine, microalbuminuria, and strain-based echocardiographic parameters, decreased PON1 activity further supports the presence of heightened oxidative stress and endothelial dysfunction in individuals at greatest cardiovascular risk." (PMID 41597318, 2025). "Another possible mechanism may be the endothelial dysfunction caused by decreased PON-1 activity." (PMID 23418418, 2013). "The activity of PON1 is supposed to be present only while it is bonded to the endothelial membrane and, in consequence, endothelial dysfunction leads to the internalization and enzymatic degradation of the enzyme." (PMID 38474211, 2024). "On the other hand, it is possible that the reduction in PON-1 levels in acutely infected animals coincides with endothelial dysfunction, as stated by others." (PMID 34551803, 2021). "The correlation matrices demonstrated strong, inverse relationships between HDL-C, ApoA-I, LDL-C, total cholesterol, and PON-1 with endothelial dysfunction markers but a positive correlation with triglycerides." (PMID 34535154, 2021). "In this study, we consistently found that glycation of PON1 not only inhibited paraoxon hydrolysis but also induced endothelial dysfunction in diabetic rats." (PMID 28374834, 2017). "In our study, the significant downregulation of PON1 in DN patients may indicate impaired antioxidant defense in the kidney, contributing to enhanced oxidative damage, endothelial dysfunction, and progression of glomerular injury." (PMID 40868959, 2025). "Endothelial dysfunction in the body can be brought on by glycosylated PON1-inducing ER stress." (PMID 36003068, 2022). "In addition, PON protein possesses PON1 and arylesterase (ARE) activity and is involved in preventing LDL oxidation and endothelial dysfunction, both of which have been linked to the pathogenesis of migraine." (PMID 35627115, 2022). "Knowing the key role of the superoxide/SERCA oxidation/Ca2+ axis in gly-PON1-induced ER stress in vitro, we finally determined whether suppression of this axis prevented gly-PON1-induced endothelial dysfunction in vivo." (PMID 28374834, 2017). "Based on the literature evidence, we hypothesized that PON1 glycation may promote endothelial dysfunction via ER stress." (PMID 28374834, 2017). "Furthermore, polymorphisms in paraoxonase 1 (PON1), an antioxidant linked to high-density lipoproteins, have been associated with endothelial dysfunction." (PMID 27932996, 2016). "Furthermore, PON-1 prevents endothelial dysfunction, commonly observed in OSA." (PMID 35453451, 2022). "In the derivation cohort, the Hypolipoprotein phenotype had significantly lower total cholesterol, HDL-C, LDL-C, PON-1, ApoA-I, and higher ICAM-1, indicative of more severe endothelial dysfunction." (PMID 34535154, 2021).
endothelial dysfunction (continued). "The results achieved during the current study demonstrated changes in the lipid parameters, endothelial dysfunction markers (tHCY, ADMA, and PON-1), and selected inflammatory markers in rabbits fed with cholesterol-rich diet with added oxidized cholesterol derivatives for 6 months." (PMID 29713239, 2018). "Glycated PON1 (Gly-PON1) instigated ER stress via the oxidation and inhibition of sarcoplasmic/endoplasmic reticulum Ca2+ ATPase (SERCA) in endothelial cells and induced endothelial dysfunction in rats." (PMID 28374834, 2017). "Importantly, injection of glycated PON1 but not native PON1 induced aberrant ER stress and endothelial dysfunction in rats, which were attenuated by tempol, BAPTA, and 4-PBA." (PMID 28374834, 2017).
hyperlipidemia (16 papers, 2009 to 2025). "The changes in gene expression caused by low PON1 expression/activity levels are exacerbated by the metabolic stress of hyperlipidemia or hyperhomocysteinemia." (PMID 39594433, 2024). "Our group found that in CAD patients with hyperlipidaemia, CpG4 methylation of the PON1 promoter resulted in low mRNA expression of PON1, leading to clopidogrel resistance." (PMID 38098098, 2023). "For example, induction of hyperlipidemia, either by a high-fat diet or ApoE gene deletion, increases atherosclerotic lesion size in Pon1−/− mice compared with Pon1+/+ animals." (PMID 33260536, 2020). "Unexpectedly, the highest PON-1 activity was obtained in the lipemic samples, as opposed to a false decrease associated with severe lipemia reported in the method validation study." (PMID 39409835, 2024). "Lipemia, as defined by an increase in the concentration of triglycerides and cholesterol, as well as prolonged freezing (−20 °C for over 6 months), appears to increase PON-1 activity when measured by the automated method based on paraoxone." (PMID 36669034, 2023). "In addition, hyperlipidemia decreased PON1 expression in Syrian hamsters." (PMID 35054478, 2022). "Our results indicate that a positive association between PON1 arylesterase and triglycerides may not be restricted to familial combined hyperlipidemia patients." (PMID 27812605, 2016).
psoriasis (16 papers, 2017 to 2025). An autoimmune condition characterized by red, well-delineated plaques with silvery scales that are usually on the extensor surfaces and scalp. "A study investigates the association between PON1 polymorphisms (rs662 and rs854560) and psoriasis susceptibility in a western Mexico population involving 104 psoriasis patients and 124 controls." (PMID 39456475, 2024). "Among the variants of PON, psoriasis patients were found to have lower PON1 activity in their blood compared to healthy individuals, indicating that psoriasis is linked to oxidative stress and a weakened antioxidant system." (PMID 39456475, 2024). "The presence of the PON1 55 M allele was determined to be associated with psoriasis using polymerase chain reaction–restriction fragment length polymorphism." (PMID 39456475, 2024). "This proposition is supported by studies reporting that anti-psoriasis treatment was associated with a significant reduction in inflammatory markers and a significant increase in PON-1 activity." (PMID 35313365, 2023). "Psoriasis is associated with the presence of paraoxonase-1gene polymorphisms that cause a low paraoxonase-1 activity, as well as an increase in oxidative stress." (PMID 35204165, 2022). "Dysfunction of PON1 is implicated in metabolic disorders, and the PON1 55 M allele is a risk factor for psoriasis with an odds ratio of 1.57 for heterozygotes and 1.97 for homozygotes." (PMID 36012327, 2022). "The fact that CRP and PON1 activity have a substantial inverse association shows that PON1 activity and inflammation are linked in psoriasis." (PMID 35888704, 2022). "Another study also revealed lower PON1 activity in psoriasis-suffering patients due to PON1 polymorphism related to decreased antioxidative activity and different lipid levels." (PMID 35313642, 2022). "For example, an enzyme with an important role in the psoriasis-associated comorbidities is paraoxonase-1." (PMID 35204165, 2022). "Similarly, lower PON1 activity correlated with higher lipoprotein levels, exacerbating oxidative stress susceptibility in psoriasis patients." (PMID 39456475, 2024). "In addition, a research study examines the correlation between the PON1 55 M allele and psoriasis in a case-control study involving 100 individuals with psoriasis and 100 healthy individuals." (PMID 39456475, 2024). "Moreover, certain polymorphisms (paraoxonase-1 55 M > L) appear to be factors that directly impact on one’s risk of developing psoriasis." (PMID 35204165, 2022). "Interestingly, PON1 55 M allele is a risk factor for psoriasis: a case-control study of 100 patients with psoriasis demonstrated an association of this allele with an impairment of the antioxidant system and an abnormal lipid metabolism." (PMID 28911329, 2017). "Furthermore, in terms of paraoxonase-1 gene polymorphisms, it was observed that the presence of the rs662 polymorphism (A > G) is more frequently associated with the development of psoriasis (p = 0.004), with affected cases being most likely carriers of the heterozygous form A/G (p = 0.003)." (PMID 35204165, 2022). "Reduced PON1 activity in individuals with psoriasis implies its role in disease pathology, contributing to oxidative stress and inflammation by disrupting the balance between ROS production and antioxidant defenses." (PMID 39456475, 2024). "We conducted a systematic review and meta-analysis of plasma/serum concentrations of PON-1 paraoxonase and arylesterase activity in psoriasis, a chronic immune-mediated and inflammatory skin disease." (PMID 35313365, 2023). "According to PASI subgroups, in patients with mild psoriasis, PON1 significantly positively correlated with WBC, CRP, PLT, Chol and AST activity." (PMID 35888704, 2022). "Our findings highlight the significant role of PTX3 and PON1 in chronic inflammation and psoriasis severity." (PMID 35888704, 2022).
psoriasis (continued). "These divergent results cited along with ours highlight the potential protective role of paraoxonase 1 in terms of the intense metaflammation in severe psoriasis." (PMID 35888704, 2022). "Patients with psoriasis exhibit low PON-1 activity, which is negatively correlated with psoriasis area and severity index (PASI) scores." (PMID 32013194, 2020). "The concentrations of malondialdehyde (MDA), SOD, CAT, total bilirubin, direct bilirubin, uric acid, apolipoproteins, and paraoxonase 1 (PON1) were measured in 100 patients with psoriasis and 100 controls." (PMID 29619128, 2018). "Notably, treatment with TNF-α inhibitors improved clinical outcomes in psoriasis patients by enhancing PON1 activity, underscoring the link between PON1 activity and inflammation." (PMID 39456475, 2024). "Although the exact mechanisms responsible for the lower serum concentrations of PON-1 activity in psoriasis are unclear, the presence of a chronic inflammatory state might play an important role." (PMID 35313365, 2023). "Another molecule with antioxidant and protective roles is paraoxonase-1 which in patients with psoriasis treated with methotrexate is present in low concentrations, possibly due to the toxic effect of methotrexate on the liver which is the synthesis site of paraoxonase-1." (PMID 35204165, 2022). "The highest level of PON1 among patients with the most severe psoriasis leads to the conclusion that the increase may be a compensation of the advanced inflammatory process." (PMID 35888704, 2022). "The PON1 55 M allele in psoriatic patients was found to be associated with higher malondialdehyde (MDA) levels, apolipoprotein B, and lipoprotein (a), suggesting interference of oxidative stress and disturbances in lipid metabolism in the pathogenesis of psoriasis." (PMID 35313642, 2022). "Presumably, PON1 might be an indicator of the liver dysfunction in psoriasis." (PMID 35888704, 2022). "By protecting from inflammation and oxidative stress, PON1 is believed to take part in the pathogenesis not only of NAFLD, but also cardiovascular or neurological disorders, which are all closely related to psoriasis." (PMID 35888704, 2022). "A cross-sectional study designed to characterize the biologic activities of plasma lipoproteins, involving 25 patients with psoriasis and 25 controls, showed lower plasma levels of HDL and reduced PON-1 activity." (PMID 28911329, 2017). "Notably, studies have investigated the antioxidant role of PON-1 and vitamin E in psoriasis, revealing reduced PON1 levels in psoriasis patients compared to controls, suggesting a potential association between decreased PON1 activity and psoriasis onset." (PMID 39456475, 2024). "There also appears to be a correlation between paraoxonase 1 levels and disease duration (p < 0.05) and between homocysteine levels and a negative family history for psoriasis (p < 0.05)." (PMID 35204165, 2022). "In contrast, in patients with severe psoriasis, significant negative correlations of PON1 with CRP and AST activity were observed." (PMID 35888704, 2022). "Therefore, we aimed to elucidate the potency of PON1 and PTX3, as they could be used as novel regulators of cardiometabolic disorders in psoriasis in terms of systemic therapy." (PMID 35888704, 2022). "Moreover, PON1 protects low density proteins (LDL) from oxidation and is therefore believed to act against the development of coronary heart disease which is reported in a higher prevalence among patients with psoriasis." (PMID 35888704, 2022). "Considering the negative correlations between paraoxonase 1 and liver enzymes activity, it can be assumed that PON1 might be a novel indicator of the liver dysfunction in psoriasis; however, further research is needed." (PMID 35888704, 2022).